TLR4 (toll like receptor 4)
Diseases named in the same sentence as TLR4 in open-access papers (continued):
Sharing a sentence is not in itself a finding about the gene and the disease.
colon carcinoma (continued). "Conversely, elevated serum levels of HMGB1 were noted in cachexia than non-cachexia colon cancer patients, and exosomes generated by the CT26 colon cancer cells induced muscle wasting like phenotype in C2C12 myotubes and mice via the activation of TLR4-nuclear factor kappa B (NF-κB) pathway." (PMID 37355693, 2023).
ischemia (147 papers, 2007 to 2026). A hypoperfusion of the BLOOD through an organ or tissue caused by a PATHOLOGIC CONSTRICTION or obstruction of its BLOOD VESSELS, or an absence of BLOOD CIRCULATION. "Allicin protects against hepatic ischemia/reperfusion injury via PPARγ/Interleukin-1 receptor-associated kinase-M (IRAK-M)/Toll-like receptor 4 (TLR4) signaling pathway." (PMID 41383463, 2025). "Modulating TLR4 signaling in vitro and in vivo was associated with attenuation of ischemia-induced skeletal muscle damage." (PMID 38510939, 2024). "The process of ischemia itself caused an increase in the expression of TLR4, NF-κB and Bax and a decrease in Bcl-2 levels, thereby contributing to increased apoptosis in the rat heart." (PMID 39338354, 2024). "Upregulation of TLR4 also occurred in ischemia in vivo and TLR4 inhibition was associated with decreased inflammatory cell infiltration and diminished apoptosis in the ischemic limb." (PMID 38510939, 2024). "In particular, the TLR4-mediated immune response has been implicated in ischemia-induced tissue injury." (PMID 38510939, 2024). "TLR4 has been shown to be induced in tubular epithelial cells in the kidney following ischemia in a MyD88-dependent manner, and TLR4-deficient mice are protected against tubular damage, suggesting that TLR4 promotes renal ischemia-reperfusion injury." (PMID 28542370, 2017). "Neuroinflammation mediated by TLR2 or TLR4 was proved to play an active role in aggravating brain damage caused by ischemia/reperfusion." (PMID 24460643, 2014). "In contrast to other recent MI/R studies with TLR4-deficient mice, we employed a closed-chest model, which allows cytokine levels to return to baseline levels after surgery and before initiation of ischemia." (PMID 17592640, 2007). "TLR4 expression was significantly upregulated in the NS-treated rats at 15 min post-ischemia, consistent with a previous study showing that TLR4 is implicated in seizures following ischemia with hyperglycemia." (PMID 36619717, 2022). "Trans-cinnamaldehyde decreases iNOS, COX-2 expression, and NF-κB signaling pathway against neuroinflammation in ischemia/reperfusion model, and cinnamaldehyde inhibits expressions of TLR4, TNF-receptor-associated factor 6, and nuclear translocation of NF-κB in permanent MCAo model." (PMID 34257822, 2021). "However, TLR4-MyD88-independent activation by damage-associated molecular patterns (DAMPs) is central to the inflammatory process in ischemia–reperfusion lesions." (PMID 29321784, 2017). "Lowered activity of genes encoding these molecules in Tlr4 KO animals suggests that the diminished ability for inflammatory cells to infiltrate the retina could elicit a neuroprotective effect following ischemia." (PMID 21031135, 2010). "We and others have shown that TLR2 and TLR4 is needed for chemokine production of murine TECs that are exposed to simulated ischemia in vitro and that renal-associated TLR is an important initiator of inflammatory responses in ischemic acute renal failure in vivo." (PMID 19479087, 2009). "Salvianolic acid D inhibited nucleoplasmic translocation of HMGB1 and its downstream TLR4/MyD88/NF-κB signaling, thereby attenuating ischemia–reperfusion brain injury." (PMID 38740617, 2025). "The TLR4-induced inflammatory response has been shown to encourage angiogenesis and collateral artery formation in various ischemia/reperfusion models, suggesting the dual role of TLR4 in inflammation and angiogenesis." (PMID 38510939, 2024). "It has been reported that eNAMPT triggers the Toll-like receptor 4/NOD-like receptor thermal protein domain associated protein three/interleukin 1β (TLR4/NLRP3/IL-1β) axis in the literature, both NAMPT and SIRT1 protect the heart from ischemia/reperfusion." (PMID 39513038, 2024). "Transient focal ischemia increases levels of TLR4 mRNA; Tlr4-/- have reduced infarct size compared with the wild-type mice." (PMID 38299364, 2024).
ischemia (continued). "Building on this work, it was shown that CD180 overexpression can ameliorate cardiomyocyte apoptosis via inhibition of TLR4 signaling and p38MAPK phosphorylation signalin ischemia/reperfusion injury rat models." (PMID 37460961, 2023). "Myeloid differentiation factor 88 (MyD88) also plays a role in TLR4‐mediated brain injury during ischemia." (PMID 37452512, 2023). "Rats that developed tonic-clonic seizures after ischemia showed significantly more TLR4-positive cells than the Sham group (77.6 ± 3.20 vs 58.6 ± 1.24, p < 0.05, n = 5 per group)." (PMID 36619717, 2022). "Ischaemia-induced NLRP3 is reduced by the administration of a TLR4 monoclonal antibody (clone HTA125) and puerarin, which partially halts the development of retinal I/R injury." (PMID 38983565, 2022). "In this study, we reported that the TLR4 pathway was involved in the pathogenesis of ischemia-induced seizures in hyperglycemic rats." (PMID 36619717, 2022). "Several studies have explored the role of HMGB1/TLR4 pathway intensification in hepatic ischemia-induced injury." (PMID 36294936, 2022). "Simultaneously, ischemia mediates retinal tissue damage and RGC death by triggering damage-associated molecular pattern-induced toll-like receptor 4 (TLR4), inflammasome-dependent neuroinflammation and microglial activation." (PMID 36289494, 2022). "Several in vivo results from other researchers illustrated that many types of agents display a nephroprotective effect in ischemia–reperfusion-induced AKI by regulating TLR4/NF-κB pathway-mediated inflammation in the kidneys." (PMID 33758309, 2021). "It is shown, that ischemia simultaneously increases the expression of Toll-like receptor-4 (TLR4) and extracellular release of ligands for this receptor from damaged nerve cells, which triggers inflammatory signaling cascades in the remaining cell populations." (PMID 34445509, 2021). "It is worth noting that there seems to be a certain contradiction to the results of other groups, who also examined the role of TLR2 and TLR4 in different ischemia/reperfusion models." (PMID 32833183, 2021). "In this study, we observed an increase of TLR4 expression after ischemia accompanied with cerebral damage and neurologic retard, which were consistent with previous findings." (PMID 33628116, 2021). "Next, we evaluated the effects of TLR4 blockade on cell viability and intracellular survival pathways when CFs were exposed only to simulated ischemia and to sI/R." (PMID 34169098, 2021). "An additional pathway influencing microglia phenotype is an alteration of TLR4 on the cell surface, that is known to significantly contribute to pro- as well as anti-inflammatory changes in ischemia or traumatic CNS injury." (PMID 33516246, 2021). "For instance, a previous study found that BMSC-derived exosomes protected against intestinal ischemia reperfusion-induced ALI via inhibition of the TLR4/NF-κB signaling pathway." (PMID 34234888, 2021). "In CXCL10−/− and TLR4−/− mice of hepatic ischemia/reperfusion injury plus major hepatectomy (IRH) model, monocytic MDSCs, instead of granulocytic MDSCs, were significantly decreased." (PMID 33990548, 2021). "Activation of TLR4 can increase enterocyte apoptosis, mucosal injury, intestinal ischemia and bacterial translocation, thus the development of NEC." (PMID 32443898, 2020). "TLR4 has also been shown to play an important role in nervous system inflammation after insults such as trauma and ischemia through observations that pharmacological inhibition of TLR4 improves outcomes after these events." (PMID 32825309, 2020). "For example, brief occlusion of the middle cerebral artery prior to extended occlusion resulted in reduced ischemia induced brain injury and these effects were, at least in part, dependent on TLR4." (PMID 31369614, 2019).
ischemia (continued). "Among the Toll-like receptors (TLR), TLR2, TLR4, and their adaptor protein, myeloid differentiation primary-response 88 (MyD88), have been reported to be involved in intestinal ischemia/reperfusion injury." (PMID 30087540, 2018). "On the contrary, recent studies demonstrated that activation of TLR4 impairs blood flow recovery after ischemia." (PMID 30460242, 2018). "A number of studies have shown that key inflammatory pathways can induce retinal damage in response to ischemia, including TLR4 and HMGB1." (PMID 30235337, 2018). "Two statin molecules, atorvastatin and simvastatin, protected rat brains from ischemic injury by significantly attenuating the overexpression of HMGB1, RAGE, TLR4, and NF-κB induced in ischemia." (PMID 28127491, 2017). "In contrast to the renoprotective role of HIF-1α, increased TLR4 expression in response to ischemia further amplifies the initial damage via activation of inflammatory mediators." (PMID 27149666, 2016). "Recently, it was shown that HMGB 1/TLR4 signaling contributed to inflammation in hepatic ischemia/reperfusion injury." (PMID 27833703, 2016). "In this pilot study, we investigated the feasibility of measuring acute HIF-1α and TLR4 expression in the peripheral circulation of pigs subjected to unilateral, ischemia-induced renal injury." (PMID 27149666, 2016). "The results from real-time PCR suggested that the expression of TLR4 gene was up-regulated in the ischemia area in MI/R group." (PMID 25260027, 2014). "With the administration of etanercept, the expression of TLR4 was significantly reduced both in the ischemia area." (PMID 25260027, 2014). "Apoptosis has been recognized as a component of a number of common cardiac pathologies, including ischemia, and the TLR4/NF-κB pathway is considered to be a major signal transduction pathway involved in cardiomyocyte apoptosis." (PMID 25187802, 2014). "Although endogenous ligands to TLR4 contribute to lung ischemia-reperfusion injury, the protective effect in Tlr4-/- mice on MCP-1/CCL2 expression and vascular barrier dysfunction were relatively small compared to that seen in Myd88-/- mice." (PMID 24146959, 2013). "Among Toll-like receptors, TLR2 and TLR4 are found to be more important than others in the pathological progression of cerebral injury due to ischemia and reperfusion." (PMID 23864765, 2013). "In our previous study, we also showed that intravenous administration of anti-TLR4 antibody 30 min prior to occlusion of the middle cerebral artery attenuated ischemia-reperfusion damage and improved mice behavioral performance." (PMID 22394415, 2012). "Microglia are activated after ischemia and undergo morphological transformation into phagocytes followed by stimulation of toll-like receptors 4 (TLR-4)." (PMID 21740583, 2011). "Taken together, these studies indicate that TLR4 signaling modulates the severity of ischemia-induced neuronal damage." (PMID 21982558, 2011). "Previous studies also demonstrated that high expression of TLR4 is positively correlated with ischemia-reperfusion injury." (PMID 20634913, 2010). "Additionally, it facilitates the secretion of BDNF and GDNF, mitigates neuroinflammation, and confers protective effects on cerebral tissues following ischemia/reperfusion injury by inhibiting the toll-like receptor 4 (TLR4)/MyD88/NF-κB pathway." (PMID 39792753, 2025). "Consequently, we investigated the potential effect of miR-125a-5p on the TLR4/NF-κB signaling pathways following the administration of EVsNC and EVsmiR in the ischemia tissues of rats after CIRI." (PMID 40585973, 2025). "We used a known model of ischemia and reperfusion (IR) in the isolated heart and hypothesized that TLR4 inhibition would reduce post ischemia damage and immune response." (PMID 39853914, 2025). "Here, we demonstrated that EVsmiR could inhibit post-ischemic inflammatory responses and thus reduce ischemia-induced neuronal injury by downregulating the TLR4/NF-κB signaling pathway." (PMID 40585973, 2025).
ischemia (continued). "It is suggested that L‐F001 may play a neuroprotective role in improving the inflammatory brain damage induced by hypoxic‐ischemia by inhibiting the activation of the TLR4 pathway." (PMID 37822185, 2023). "CD14 is a co-receptor for Toll-like receptor 4 (TLR4), both of which increase following microglia activation and play a role in the microglia response to ischemia after they are activated by endogenous damage associated molecular patterns (DAMPs) such as ATP released from dying neuron." (PMID 36721258, 2023). "Furthermore, experimental overexpression of miR-140-5p attenuated neuroinflammation and apoptosis in the brain after intracerebral hemorrhage or ischemia via TLR4 of the NFκB pathway." (PMID 37584866, 2023). "Finally, these results indicated that downregulation of the TLR4/NF-κB pathway after ischemia by HMGB2 inhibition was a potential mechanism for the neuroprotective effect of cerebral injury." (PMID 35966335, 2022). "Finally, these results indicated that the downregulation of the TLR4/NF-κB pathway after ischemia by HMGB2 inhibition is a potential mechanism of the neuroprotective effect of cerebral injury." (PMID 35966335, 2022). "Our findings indicate that the TLR4 pathway is involved in the pathogenesis of ischemia-induced seizures in hyperglycemic rats and that UTMD technology may be a promising strategy to treat brain diseases." (PMID 36619717, 2022). "We investigated whether ultrasound-targeted microbubble destruction (UTMD)-mediated delivery of short hairpin RNA (shRNA) targeting the TLR4 gene (shRNA-TLR4) can reduce ischemia-induced seizures in rats with hyperglycemia." (PMID 36619717, 2022). "The present study aimed to investigate the efficiency of UTMD-based shRNA delivery for silencing TLR4 gene expression and whether TLR4 silencing can prevent ischemia-induced seizures in hyperglycemic rats." (PMID 36619717, 2022). "To explore whether MFSCE protected against ischemia-induced neuronal cell injury through the TLR4/NF-κB pathway, we performed Western blotting." (PMID 35454994, 2022). "THP may exert protective function by raising the expression of TLR4 and its targeting to the apical membrane of proximal tubular S3 segments, where the interaction of TLR4 with pro-inflammatory interstitial ligands is released after ischemia." (PMID 34782019, 2021). "It has been shown that KOR activation by U50488H inhibits the TLR4/NF-κB signaling in an ischemia–reperfusion injured rat heart model, which suggests that dynorphin activation of KOR may also inhibit TLR4/NF-κB signaling." (PMID 32206297, 2020). "Next, in order to further investigate whether microglia and astrocyte activation are mediated by TLR4 and NF-κB, we measured TLR4, phospho-NF-κB (P-NF-κB), and NF-κB expression levels in the ischemia penumbra." (PMID 32917229, 2020). "Interestingly, two largely used cholesterol-lowering drugs, namely atorvastatin and simvastatin, significantly diminished the overexpression of HMGB1, RAGE, TLR-4, and NF-kB induced by ischemia." (PMID 32679721, 2020). "Additionally, CSO treatment significantly inhibited TLR4 and NF-κB expression in the ischemia penumbra." (PMID 32917229, 2020). "Interestingly, HA tetrasaccharides can improve outcomes after spinal cord injury in a CD44 and TLR4 dependent manner, and also protect hippocampal neurons during ischemia through the inhibition of TLR2 signaling." (PMID 32825309, 2020). "Moreover, downregulation of CXCL12/CXCR4 inhibits glial TLR4 activation in the spinal cord and alleviates pain in the ischemia-reperfusion-induced inflammatory pain model." (PMID 30647535, 2018). "TLR4 is one of the most studied TLRs from the perspective of blood flow recovery after ischemia." (PMID 30460242, 2018). "An HMGB1-TLR4 axis is active upon myocardial ischemia/reperfusion injury and the innate immune adaptor MyD88 downstream TLR4 has been shown to mediate neutrophil recruitment and myocardial injury after ischemia-reperfusion in mice." (PMID 28667492, 2017).